CDC20 (cell division cycle 20)
Diseases named in the same sentence as CDC20 in open-access papers (continued):
Sharing a sentence is not in itself a finding about the gene and the disease.
cancer (continued). "Here we report that, based on the PROTAC platform, we have developed a potent chemical molecule named CP5V, which can induce robust Cdc20 proteolysis and inhibit cancer cell proliferation." (PMID 31669221, 2019). "The relatively high expression of Cdc20 has been regarded as a clinicopathological parameter in many types of human cancers as well." (PMID 31669221, 2019). "Single-cell results have confirmed that knockdown of Cdc20 by siRNA can effectively prolong the time of cancer cells to be arrested in the mitosis phase and can efficiently promote cell death during mitotic arrest." (PMID 31669221, 2019). "Results from TCGA (The Cancer Genome Atlas) and pathological analysis have revealed a strong connection between aberrant upregulation of Cdc20 and various types of cancers." (PMID 31669221, 2019). "CDC20 is a cell cycle protein and its overexpression can promote the proliferation and inhibit the apoptosis of cancer cells." (PMID 31275405, 2019). "Cdc20-APC/C is a master regulator of mitosis, whose deregulation is tightly linked to various cancers." (PMID 31669221, 2019). "We observed CP5V showed its ability to induce Cdc20 degradation and growth inhibition in all tested cancer cell lines, suggesting the broad effect of CP5V in various cancer type cells." (PMID 31669221, 2019). "Inhibitors of CDC7 and CDC20 kinases would be promising candidates for novel classes of cancer drugs." (PMID 30363964, 2018). "Apart from the cell cycle control, it was also proved that CDC20 plays an important role in the development of human cancers." (PMID 30563222, 2018). "Support for this idea comes from studies using SIRT2, an antitumor and lifespan-extending protein, which activates the APC by deacetylating CDC20 and CDH1; SIRT2-deficient mice exhibited higher levels of cancer and elevated levels of APC substrates." (PMID 29954095, 2018). "In many cancer cell lines, its knockdown inhibits cell division/proliferation, and cdc20 overexpression greatly promotes cell division/proliferation." (PMID 28659168, 2017). "Higher expression of Cdc20 has been observed in a variety of human cancers and is correlated with poor prognosis." (PMID 28165402, 2017). "The levels of expression of SMAR1 were significantly repressed while those of Cdc20 were significantly elevated with increasing grades of cancer further supporting the in vitro cell lines results." (PMID 28617439, 2017). "Collectively, our results suggest that Cdc20 augments cell migration of cancer cells by proteasomal degradation of SMAR1, at least in part." (PMID 28617439, 2017). "One study has revealed that Cdc20 inhibited cell apoptosis via degradation of Bim in human cancer cells." (PMID 28165402, 2017). "This is in agreement with other cancer types where an upregulated Cdc20 expression correlated with a poor prognosis." (PMID 26716651, 2016). "Further results based on mouse targeting deletion or xenograft studies demonstrated that APC/C coactivator Cdc20 or Cdh1 to be as oncoprotein or tumor suppressor in many types of cancer." (PMID 27418942, 2016). "Blocking mitotic exit by Cdc20 knockdown was shown to inhibit mitosis slippage and overcome apoptosis-resistant in cancer cells." (PMID 27611665, 2016). "Recently, studies have shown that Cdc20 maintains tumor initiation cells and serves as a potential target for cancer treatment." (PMID 26993778, 2016). "Concomitant with downregulation of Cdh1 expression, several APC/C–Cdh1 targets, such as Aurora A, Aurora B, Cdc6, Cdc20, Cyclin B, Rad17 and Tpx2 are often upregulated in human cancer tissue samples." (PMID 27418942, 2016). "Emerging evidence has demonstrated that Cdc20 plays an oncogenic role in the development and progression of human cancers." (PMID 27626499, 2016). "Cell cycle kinases (e.g. CDC2, CDC5, CDC7 and CDC20) as well as AURKA and S100A9, which can all broadly be linked to cell cycle regulation and mitosis, were upregulated in the malignant tumors." (PMID 25226589, 2014).
cancer (continued). "Another study also found that treatment of cancer cells with siRNA against CDC20 successfully induced G2/M arrest and suppressed cell growth." (PMID 23758705, 2013). "Cdc20 protein expression level was also variable in used cancer cells lines, but Cdc20/Mad2 protein expression ratio seems to be dispensable for taxol resistance compared to p31comet/Mad2 ratio." (PMID 24255856, 2013). "Meta-analysis of cancer microarray data also identifies CDC20 as one of the highly expressed genes in various human cancer tissues." (PMID 23738901, 2013). "It is reported that Cdc20 functions as an oncoprotein to promote the development and progression of human cancers." (PMID 23738901, 2013). "Given the crucial oncogenic role of CDC20 in tumorigenesis, targeting its inhibitors may offer a therapeutic advantage for human cancer." (PMID 40439120, 2025). "Overexpression of CDC20 promoting cancer cell division could be a driving force behind the aggressiveness seen in GS 10 patients." (PMID 40227503, 2025). "CDC20 plays a crucial role in cell cycle regulation and cancer therapy." (PMID 40439120, 2025). "In contrast, CDC20 is frequently overexpressed in various types of cancers and is oncogenic." (PMID 41374402, 2025). "Current studies suggest that CCNB1, TTK, and CDC20 are overexpressed in various cancers." (PMID 40181976, 2025). "To evaluate whether the differential response of aneuploid human cancer cell lines to SAC inhibitors is indeed related to their increased CDC20 expression, we assessed the effect of CDC20 expression on the association between aneuploidy and drug response." (PMID 39838194, 2025). "This interaction suggests that Pixuvri may inhibit the activation of the anaphase-promoting complex (APC) by targeting Cdc20, thereby disrupting cell division and potentially inducing apoptosis in cancer cells." (PMID 40519296, 2025). "Emerging evidence suggests that APC/C and its co-activators (CDC20/CDH1) may influence cancer progression beyond cell cycle regulation, potentially through modulation of EMT and MMP pathways." (PMID 40136519, 2025). "In vitro experiments enable us to meticulously investigate the direct effects and regulatory mechanisms of CDC20 in human cancer cells, whereas in vivo experiments offer the opportunity to assess the impact and applicability of these mechanisms within a physiological environment." (PMID 39114311, 2024). "CDC20 enhances the proliferation, invasion, and metastasis of cancer cells through the CDC20-mediated angiogenesis pathway, highlighting its role in promoting angiogenesis in cancer tissues." (PMID 39795587, 2024). "CDC20 is often overexpressed in multiple cancer types and exhibits oncogenic characteristics." (PMID 39795587, 2024). "Therefore, CDC20 is an important research target in cell biology and cancer research, essential for deepening our understanding of cell division, the pathogenesis of cancer, and potential therapeutic avenues." (PMID 39518808, 2024). "This deeper understanding of CDC20’s role in gene regulation, protein interactions, and cell signaling pathways will enhance our understanding of the pathogeneses of various human diseases such as cancer, neurological disorders, and immune system diseases." (PMID 39518808, 2024). "For example, the APC/C:Cdc20 pathway is critical for the proper segregation of chromosomes during cell division, and its dysregulation can result in aneuploidy and chromosomal instability, which are common features of aggressive cancers." (PMID 39201599, 2024). "Survival analysis revealed that increased CCNB1 expression and advanced cancer stage were associated with poorer overall survival, whereas no significant impact of CDC20 expression or tumor grade on survival was observed." (PMID 39795587, 2024). "As tumor-infiltrating immune cells play a crucial role in cancer incidence, progression, and metastasis, we investigated whether CDC20 expression was correlated with immune infiltration levels in BC using the TIMER database." (PMID 39061186, 2024).
cancer (continued). "Olomoucine may limit tumor growth by blocking both CDK1 and its downstream effects on CDC20, particularly in cancers with dysregulated pathways." (PMID 39457373, 2024). "Additionally, HCT116 cells were also selected to investigate the potential role and mechanism of CDC20 in pan-cancer." (PMID 39125953, 2024). "Additionally, olomoucine, by targeting CDK1 and CDC20, aligns with observed dysregulation in mitotic pathways, suggesting a strategic approach to limit cancer cell proliferation." (PMID 39457373, 2024). "Moreover, these cells expressed the CDC20 gene, encoding cell division cycle protein 20 homolog, which can function as an oncoprotein, and BIRC5, which inhibits apoptosis; both promote cancer progression, and are poor prognostic markers in cancer patients." (PMID 39405604, 2024). "In DOX-surviving proliferative cells, we found positively correlated gene pairs, for example, two senescent markers (GDF15 and CDKN1A R= 0.54) and anticorrelated gene pairs, for example, GDF15 and genes involved in cancer progression: CDC20 (R= -0.26) and BIRC5 (R= -0.17)." (PMID 39405604, 2024). "In addition, inactivation of Cdc20 sensitized cancer cells to treatment with the ER stress inducer in a TPD52‐dependent manner." (PMID 39401430, 2024). "The results consistently supported our hypothesis that CDC20 knockdown could sensitize cancer cells to both cisplatin and etoposide in a dose-dependent manner." (PMID 39125953, 2024). "In line with this, CDC20 overexpression was previously found in many human cancers." (PMID 39061186, 2024). "CDC20 is overexpressed in many cancers and has been identified as a potential treatment target." (PMID 39125953, 2024). "Lastly, our functional research demonstrated that knocking down CDC20 could inhibit cancer cell migration, invasion, proliferation, cell cycle progression, and tumor growth possibly through the MAPK signaling pathway." (PMID 39114311, 2024). "The APC substrate, CDC20, an APC co-activator in mitosis, is frequently highly overexpressed in different cancer cell lines and human tumors, leading to consideration that elevated CDC20 is an important driver of tumorigenesis, and can serve as a prognostic marker, and a therapeutic target." (PMID 38730707, 2024). "According to the TCGA database, we evaluated CDC20 expression levels in various cancer types." (PMID 39061186, 2024). "On the other hand, CDC20 was revealed as an oncoprotein that promotes human cancer progression." (PMID 38806527, 2024). "Therefore, a comprehensive analysis of the functions and molecular mechanisms of CDC20 in pan-cancer is essential to gain advanced insights into relevant cancer mechanisms and enlighten strategies for anticancer drug development." (PMID 39061186, 2024). "Given the important oncogenic role of CDC20 in tumorigenesis, targeting CDC20 may interfere with mitosis, thereby inhibiting cancer proliferation." (PMID 37682144, 2023). "Multiple studies have suggested that CDC20 plays a role in the oncogenesis of human cancers." (PMID 37383715, 2023). "TOP2A, CENPF, TROAP, CDC20, CDCA5, and UBE2C are all reported to be associated with cancer." (PMID 36932399, 2023). "Another oncogenic Cdc20 subunit in the APC/C complex may be a therapeutic target for cancer treatment." (PMID 37341064, 2023). "Suppressing CDC20 could be a promising strategy to overcome resistance to antitumor therapy in various cancers." (PMID 37682144, 2023). "CDC20 is also a regulator of cell cycle checkpoints, and its increased expression is related to poor pathological features and poor prognosis in a variety of human cancers." (PMID 37719710, 2023). "Regulation of Cdc20 in various human cancers to exert its anti-tumor activity." (PMID 37682144, 2023). "Compound 27 emerged as Cdc20 inhibitor is valuable in cancer treatment." (PMID 37259447, 2023). "Many compounds have been identified as potential anti‐cancer drugs by targeting Cdc20." (PMID 37341064, 2023).
cancer (continued). "Downregulate the expression of CDC20 in cancer cells, the specific mechanism is till under study." (PMID 37682144, 2023). "In addition to its pivotal role in regulating cell cycle progression, CDC20 has been reported to have oncogenic effect due to its overexpression in a broad spectrum of cancers." (PMID 36882855, 2023). "CDC20 is one of the cell cyclins, which is highly expressed in most tissues with malignant tumors." (PMID 35945960, 2022). "Cdc20 is a potential biomarker and an ideal target for cancer treatment." (PMID 35680848, 2022). "In the future, CDC20 will be used in many other cancer therapies." (PMID 35800227, 2022). "Patients who had higher cancer stages (stage 1–3) tended to have higher CDC20 expression, while patients with stage 4 showed low expression of CDC20, which may be due to the small sample size and other factors." (PMID 35622386, 2022). "Our findings shared new insights into the implication of the CDC20–hnRNPU axis in regulating chromatin organization and drug resistance, suggesting that the CDC20–hnRNPU axis could be a good target for cancer therapy." (PMID 35954396, 2022). "Furthermore, many studies have figured out that CDC20 is a carcinogen that promotes cancer development." (PMID 35280820, 2022). "The results of immunohistochemical staining showed that in the 10 pairs of KIRC tissue blocks, the expression of CDC20 was higher than that of the corresponding normal tissue adjacent to cancer, and the degree of the increased CDC20 expression was individually different." (PMID 35800227, 2022). "Up to this point, it is also interesting to note that most of the GO and KEGG terms based on the DEGs like CCNB1, PLK1 and CDC20 are closely related to anti-cancer patterns, which may point to the anti-cancer potential of our MOL extract preparation." (PMID 36197921, 2022). "Therefore, we commented on the potential of CDC20 as a target for the treatment of human malignant tumors based on the bioinformatics database." (PMID 35800227, 2022). "Increased accumulation of these APC substrates in many aggressive cancers has led to suggestions that therapies that down-regulate these targets, such as CDC20 or others, may be important for augmenting cancer treatment responses." (PMID 36077749, 2022). "CDC20 was reported in large amounts to exert its oncogenic role in different types of cancers." (PMID 35622386, 2022). "Notably, as an activator of APC/C during mitosis, CDC20 is an important regulator of the cell cycle and plays a role in cancer emergence and development." (PMID 35804892, 2022). "Many studies have focused on the biological role of CDC20 in cancer development, as alterations of its functionality have been linked to genomic instability and evidence demonstrated that high CDC20 expression levels are associated with poor overall survival in solid cancers." (PMID 35490245, 2022). "Apart from that, UBE2C and CDC20 can also be found in other cancers." (PMID 36385010, 2022). "This study unveils a new view for CDC20 in regulating chromatin dynamics and uncovers the molecular mechanism by which CDC20 modulates drug resistance, which provides a novel strategy for developing anti-cancer therapy." (PMID 35954396, 2022). "CDC20 may be a valuable prognostic predictive biomarker and a potential therapeutic target in various cancer parents." (PMID 36479068, 2022).
cancer (continued). "Overall, our study not only identifies a detailed mechanism for CDC20 gene deregulation in human cancers but also finds functional noncoding genetic alterations, with implications for the further development of function-based noncoding driver discovery pipelines." (PMID 33851100, 2021). "CDC20 knockdown was shown to sensitize cancer cells to chemotherapy and radiation therapy." (PMID 34266348, 2021). "In nearly all types of cancers analyzed, elevation of CDC20 mRNA expression is observed." (PMID 33851100, 2021). "Therefore, scatter plots were applied to visualize the ranks of Cdc20 and its substrates(p21, CyclinB1, and Bim) in specific cancer types." (PMID 34527589, 2021). "CDC20 has been found to be a potential therapeutic target and biomarker for a variety of cancers." (PMID 34512169, 2021). "The landscape of CDC20 gene expression and its biological impacts across different types of cancers remains largely unknown." (PMID 34527589, 2021). "Additionally, treatment of cancer cells with siRNA against CDC20 can induce G2/M arrest and inhibit cell growth." (PMID 33446695, 2021). "Based on this evidence, it is indicated that the phosphorylated Cdc20 could be more functional active in performing its oncogenic role in cancer." (PMID 34527589, 2021). "The role of CDC20 in the infiltration of immune cells in the tumor microenvironment was demonstrated, which may guide cancer treatment and targeted drug development." (PMID 34512169, 2021). "In addition, the expression and function of Cdc20 were further validated in our clinical samples and cancer cell lines, and immune-competent mice models." (PMID 34527589, 2021). "E3 ligases, or particular components of their complexes (MDM2, IAP, APC/CDC20, and others), are known as oncogenes or tumor suppressors in numerous types of cancer; thus, they may serve as potential cancer targets or are themselves “druggable” enzymes." (PMID 34502538, 2021). "Taken together, these data support an oncogenic driving function of CDC20 in human cancer." (PMID 33851100, 2021). "Importantly, recent studies have reported a group of specific inhibitors of Cdc20 in the pre-clinical model of different kinds of cancer." (PMID 34527589, 2021). "In addition, in human malignant tumors, inhibition of CDC20 in growing cells leads to G2 arrest with a consequent decrease of cyclin B1, securin, and cyclin A." (PMID 34513754, 2021). "Firstly, the cancer types with significantly elevated CDC20 gene in the previous analysis were selected, and the expression of CDC20 was significantly and positively correlated with the increase of clinical stages in indicated cancers types, including ACC, BRCA, KIRC, LUAD, (P<0.05)." (PMID 34527589, 2021). "It is probably that the specific substrates of Cdc20 across all types of human cancers remain largely unknown." (PMID 34527589, 2021). "In addition, depleting CDC20 in various cancer cell lines led to the blockade of mitotic followed by cell death." (PMID 34527589, 2021). "Moreover, Spain, a more specific Cdc20 inhibitor, inhibits the oncogenic function of Cdc20 by directly interfering with the interaction between Cdc20 and its substrates, leading to the blockade of mitotic exit in human cancer cells." (PMID 34527589, 2021). "Previous studies reported that CDC20 is overexpressed in various human cancers." (PMID 33851100, 2021). "We further analyzed genetic alterations in CDC20 genes based on public cancer genome databases." (PMID 33851100, 2021). "Many studies suggest that CDC20 is overexpressed in many cancers." (PMID 34603487, 2021). "Here we have identified CDC20 plays a key role in the various human cancers." (PMID 34527589, 2021). "Furthermore, Cdc20 is able to target the tumor suppressor SMAR1 for polyubiquitination degradation in kinds of cancers, such as breast cancer, cervical and colon cancer." (PMID 35006464, 2021). "Overexpression of CDC20 is correlated with clinicopathological parameters of various cancers." (PMID 33851100, 2021).